OLFM1 (olfactomedin 1)
Description:
Contributes to the regulation of axonal growth in the embryonic and adult central nervous system by inhibiting interactions between RTN4R and LINGO1. Inhibits RTN4R-mediated axon growth cone collapse (By similarity). May play an important role in regulating the production of neural crest cells by the neural tube (By similarity). May be required for normal responses to olfactory stimuli (By similarity).
Synonyms: NOE1; OlfA; AMY; NOELIN; NOELIN1
Tractability: Antibody: UniProt places it where antibodies can reach, with medium confidence; UniProt predicts a signal peptide or a membrane-spanning region; its Gene Ontology location is reachable by antibodies, with medium confidence. PROTAC: ubiquitination databases record sites on it; its protein half-life has been measured.
Gene: Protein-coding gene on chromosome 9 (135,075,422 to 135,121,180, forward strand). Ensembl gene ENSG00000130558.
Subcellular location: Secreted; Synapse; Endoplasmic reticulum; Cell projection, axon; Perikaryon
Subcellular location (Human Protein Atlas): Nucleoli; Cytosol; Nucleoplasm; Predicted to be secreted
Gene Ontology:
Molecular function: protein binding
Biological process: positive regulation of apoptotic process; atrioventricular valve formation; cardiac epithelial to mesenchymal transition; negative regulation of gene expression; nervous system development; neuronal signal transduction; positive regulation of epithelial to mesenchymal transition; positive regulation of gene expression; regulation of axon extension; signal transduction; regulation of neurotransmitter receptor localization to postsynaptic specialization membrane
Cellular component: axon; axonal growth cone; endoplasmic reticulum; extracellular region; neuronal cell body; perikaryon; synapse
Genetic constraint (gnomAD): Loss-of-function variants: 9 observed, 47.91 expected, observed/expected ratio (o/e) 0.19, 90% interval 0.11 to 0.33. The upper end of that interval is the gene's LOEUF score, 0.33, which puts it in group 1 of 6, group 1 being the genes least tolerant of losing a copy. Missense variants: 369 observed, 651.09 expected, observed/expected ratio (o/e) 0.57, 90% interval 0.52 to 0.62. Synonymous variants: 240 observed, 264.5 expected, observed/expected ratio (o/e) 0.91, 90% interval 0.82 to 1.01.
Homologues: Orthologues: chimpanzee OLFM1 (100% identical), dog OLFM1 (98% identical), mouse Olfm1 (98% identical), rat Olfm1 (98% identical), pig OLFM1 (97% identical), tropical clawed frog olfm1 (93% identical), guinea pig OLFM1 (93% identical), zebrafish olfm1a (84% identical), zebrafish olfm1b (84% identical), macaque OLFM1 (39% identical). Paralogues in human: OLFM3 (60% identical), OLFM2 (54% identical), OLFML2B (27% identical), OLFML2A (26% identical), MYOC (26% identical), OLFM4 (25% identical), GLDN (21% identical), OLFML3 (20% identical), OLFML1 (19% identical).
Diseases named in the same sentence as OLFM1 in open-access papers:
OLFM1 is named in the same sentence as 39 diseases in open-access papers, as found by Europe PMC text mining. Sharing a sentence is not in itself a finding about the gene and the disease. The quoted sentences say what the papers report.
neuroblastoma (5 papers, 2010 to 2025). Neuroblastoma (NB) is the most common solid, extracranial childhood tumor. "OLFM1 is related to nervous system development and Neuroblastoma." (PMID 29671403, 2018). "Currently, diseases related to olfactomedin 1 (OLFM1) include myopathy and neuroblastoma, with this gene showing significant expression in brain cancer datasets." (PMID 40608007, 2025). "Recently, olfactomedin-1 has been identified as an environmental signal produced by chick embryonic sympathetic ganglia and able to trigger NMT and dissemination of neuroblastoma cells in an avian model." (PMID 37142597, 2023).
depression (4 papers, 2021 to 2025). "For interaction analysis, we detected that OLFM1 interacted with champagne/white wine in depression, while SYNPO2 interacted with coffee type in fluid intelligence." (PMID 33807197, 2021). "Genes like NRG1, OLFM1, and WDR62, associated with both tumor progression and neuropsychiatric symptoms such as fatigue and depression, highlight the neuroimmune signature as a potential marker of disease severity and a target to mitigate extrahepatic manifestations in chronic hepatitis." (PMID 41347690, 2025). "Our result suggests that OLFM1 gene expression may be involved in the mechanism between champagne/white wine and depression." (PMID 33807197, 2021).
colorectal cancer (3 papers, 2023 to 2025). A primary or metastatic malignant neoplasm that affects the colon or rectum. "Although the exact function of this protein is unknown, some studies suggested that decreased OLFM1 expression is associated with tumorigenesis, increased malignant potential, and worse progression-free survival and OS in colorectal cancer, endometrial cancer, and thyroid carcinoma." (PMID 41259663, 2025). "Consistently, OLFM1 could inhibit the growth and metastasis of colorectal cancer cells through affect the NF-κB signalling pathway." (PMID 37377953, 2023). "In colorectal cancer (CRC) cells, OLFM1 inhibits the non-canonical nuclear factor-kappa B (NF-κB) signaling pathway, which plays a pivotal role in the proliferation and activation of immune cells." (PMID 38932372, 2024).
insomnia (2 papers, 2021 to 2022). A sleep disorder characterized by difficulty in falling asleep and/or remaining asleep. "Cognitive dysfunction was found to be mainly associated with anti-olfactomedin 1 (OLFM1) antibodies, and sleep dysfunction (insomnia) in patients was associated with anti-Gamma-crystallin N (CRYGN) antibodies." (PMID 35711412, 2022). "Furthermore, six autoantibodies were associated with specific psychopathology symptoms: anti-AP3B2 (persecutory delusions), anti-TDO2 (hallucinations), anti-CRYGN (initial insomnia); anti-APMAP (poor appetite), anti-OLFM1 (above-median cognitive function), and anti-WHAMMP3 (anhedonia and dysphoria)." (PMID 34518517, 2021).
abortion (1 paper, 2021). the ending of pregnancy by removing a fetus or embryo before it can survive outside the uterus. "A higher expression of OLFM1 was found in endometrial tissues from patients with unexplained recurrent spontaneous abortion." (PMID 34831106, 2021).
amyotrophic lateral sclerosis (1 paper, 2021). Amyotrophic lateral sclerosis (ALS) is a neurodegenerative disease characterized by progressive muscular paralysis reflecting degeneration of motor neurons in the primary motor cortex, corticospinal tracts, brainstem and spinal cord. "OLFM1 was also demonstrated to be related to amyotrophic lateral sclerosis due to its regulation of motor cortex and spinal cord." (PMID 33807197, 2021).
Anxiety (1 paper, 2018). Intense feelings of nervousness, tension, or panic often arise in response to interpersonal stresses. "In contrast to Olfm1, genetic targeting of Olfm2 did not result in gross abnormalities but mutant mice presented with abnormal locomotor coordination, reduced exploration and anxiety-related behavior." (PMID 30093905, 2018).
Autoimmunity (1 paper, 2021). The occurrence of an immune reaction against the organism's own cells or tissues. "Our findings raise the intriguing possibility, to be investigated in future studies, that OLFM1-autoimmunity could be protective against such effects." (PMID 34518517, 2021).
brain ischemia (1 paper, 2023). Diminished or absent blood supply to the brain caused by obstruction (thrombosis or embolism) of an artery resulting in neurologic damage. "For instance, OLFM1 plays a role in the biological process of brain ischemia and axon growth." (PMID 37280213, 2023).
diabetic neuropathy (1 paper, 2025). A chronic, pathological complication associated with diabetes mellitus, where nerve damages are incurred due to diabetic microvascular injury involving small blood vessels that supply these nerves, resulting in peripheral and/or autonomic nerve dysfunction. "Similarly, OLFM1 is implicated in neuronal development and may contribute to the regulation of synaptic plasticity, which is perturbed in diabetic neuropathy." (PMID 40692573, 2025). "In addition, further research is needed to explore the roles of specific biomolecules implicated in diabetic neuropathy development, such as SLC30A1, TRBJ2‐7, OLFM1, TCF7L2, MCF2L, CEP295NL, CEACAM22P, TSHZ2, and PDZD4." (PMID 40692573, 2025).
Ewing sarcoma (1 paper, 2014). A small round cell tumor that lacks morphologic, immunohistochemical, and electron microscopic evidence of neuroectodermal differentiation. "Strong connection links on certain genes (TNNT1 and FNDC5 in rhabdomyosarcoma (RMS); FCGRT and OLFM1 in Ewing’s sarcoma (EWS)) suggested their potency as central hubs in the interconnection of genes with different functionalities." (PMID 25025207, 2014).
metastatic disease (1 paper, 2022). "Whatever the case, the targeting of OLFM1 achieved in our studies resulted in significant beneficial consequences on the metastatic disease." (PMID 35538114, 2022).
multiple sclerosis (1 paper, 2024). A progressive autoimmune disorder affecting the central nervous system resulting in demyelination. "Like APLP1, OLFM1 is an understudied player in multiple sclerosis, yet it demonstrates relevant and interesting neurobiology." (PMID 38880880, 2024). "We also examined how OLFM1 can predict disease subtype of multiple sclerosis." (PMID 38880880, 2024).
primary progressive MS (1 paper, 2024). "Of particular significance was the discovery that low levels of APLP1 and CNDP1, or high levels of OLFM1, may distinguish relapsing remitting MS patients from primary progressive MS." (PMID 38880880, 2024).
schizophrenia (1 paper, 2021). A major psychotic disorder characterized by abnormalities in the perception or expression of reality. "Moreover, OLFM1 is part of the disrupted in schizophrenia 1 (DISC1) protein interactome, variations of which were shown to increase the risk of poorer childhood cognitive performance in people who later developed SCZ." (PMID 34518517, 2021).
tumor (6 papers, 2013 to 2025). "One of these studies suggested that decreased expression of OLFM1 accelerates tumor progression through activation of the NF-κB signaling." (PMID 41259663, 2025). "Here, we provide the evidence that physiological signals expressed during embryonic peripheral ganglia organogenesis, including OLFM1, are exploited by NB cells to escape from the primary tumor site and engage in metastasis." (PMID 35538114, 2022). "Our in vivo analysis indicates that some NB cells disseminate at lower distance from the primary tumor upon OLFM1 blockade." (PMID 35538114, 2022). "This suggested that interfering with OLFM1-mediated signaling alters NB cell escape from the primary tumor and subsequent migratory and invasive steps, leading to an aborted metastatic process, while not affecting the proliferative state of NB cells." (PMID 35538114, 2022). "Second, NB cells reacted to exogenous recombinant OLFM1 exposure by downregulating the contacts with their neighbors in the tumor mass and switching towards a migratory state, acquiring mesenchymal features." (PMID 35538114, 2022). "On the other hand, inhibition of OLFM1 in the primary tumor could imprint a sustained difference on NB cells, conferring them lower migration capabilities." (PMID 35538114, 2022). "We next studied whether blocking OLFM1 within NB primary tumor microenvironment could impact on NB propensity to metastasize." (PMID 35538114, 2022). "It remains unclear whether NB cell detachment primed by OLFM1 in the primary tumor influences subsequent steps of NB metastatic progression, particularly NB cell migration properties and dissemination paths." (PMID 35538114, 2022). "We show that NC-derived peripheral ganglia -the dorsal root ganglia (DRG) and the sympathetic ganglia- produce exogenous factors including OLFM1 that set a specific transcriptomic program in NB cells, promoting their detachment from the primary tumor and their metastatic dissemination." (PMID 35538114, 2022). "Interestingly, the mitotic rate of tumor cells quantified by PH3 immunolabeling was strictly similar in control and OLFM1 Ab-treated groups, showing that NB cell proliferation was unaffected by OLFM1 Ab treatment." (PMID 35538114, 2022).
cancer (3 papers, 2008 to 2025). A tumor composed of atypical neoplastic, often pleomorphic cells that invade other tissues. "Genes encoding for proteins TPRKB, T-Complex 1 (TCP1), Olftactomedin 1 (OLFM1), LDOC1 and HTRA3 have been implicated positive or negatively in cancer progression." (PMID 18793431, 2008).
OLFM1 also shares sentences with these, for which no sentence is quoted: endometrial cancer (2 papers); Alzheimer disease (1); brain cancer (1); cervical cancer (1); chronic hepatitis (1); Delusion (1); dysphoria (1); endometriosis (1); glioblastoma (1); glioma (1); Hallucinations (1); heart disease (1); idiopathic pulmonary fibrosis (1); myopathy (1); neurodegenerative disease (1); prostate carcinoma (1); relapsing remitting MS (1); rhabdomyosarcoma (1); sleep dysfunction (1); squamous cell carcinoma (1); thyroid carcinoma (1); vitiligo (1).